RNU6-905P (RNA, U6 small nuclear 905, pseudogene)
Gene: Small nuclear RNA gene on chromosome 3 (14,530,982 to 14,531,088, reverse strand). Ensembl gene ENSG00000207163.
Homologues: Orthologues: chimpanzee U6 (95% identical), macaque U6 (92% identical), mouse Gm26430 (90% identical), rabbit U6 (89% identical), dog U6 (87% identical), rat U6 (84% identical), guinea pig U6 (82% identical), guinea pig U6 (79% identical), guinea pig U6 (71% identical), mouse Gm23326 (69% identical), rat LOC120094415 (67% identical). Paralogues in human: RNU6-12P (89% identical), RNU6-13P (89% identical), RNU6-32P (89% identical), RNU6-1 (88% identical), RNU6-1024P (88% identical), RNU6-16P (88% identical), RNU6-17P (88% identical), RNU6-18P (88% identical), RNU6-19P (88% identical), RNU6-2 (88% identical), RNU6-3P (88% identical), RNU6-41P (88% identical), and 1288 more.